SIRT2 (sirtuin 2)
Diseases named in the same sentence as SIRT2 in open-access papers (continued):
Sharing a sentence is not in itself a finding about the gene and the disease.
breast cancer (continued). "Notably, the TM pseudopeptide decreased tumor size or increased overall survival in two mouse models of breast cancer and induced a G1/G0 cell cycle arrest in MCF7 cells via reduced expression of the oncogene c-Myc, indicating that Sirt2 is an attractive therapeutic target in breast cancer." (PMID 38474697, 2024). "Alternatively, SIRT2 regulates the reversible acetylation of PHGDH through TIP60 and promotes the binding of PHGDH and RNF5 to induce PHGDH degradation, which reduces the serine and glycine levels and disturbs redox homeostasis, thereby inhibiting breast cancer cell proliferation." (PMID 36101744, 2022). "Interestingly, SIRT2 expression was decreased in breast cancer tissues, but increased in metastatic tissues compared to normal tissues." (PMID 35845599, 2022). "Finally, it should not be forgotten that SIRT2 has been identified as having both cancer-promoting functions (i.e., through stabilization of Myc oncoproteins in breast cancer, as well as cancer-suppressing functions (i.e., through tubulin regulation)_." (PMID 33705642, 2021). "Furthermore, SIRT2 and CD8+TEM showed a positive correlation in breast cancer patients." (PMID 33061819, 2020). "Experimental study in vivo had demonstrated that decreased HR efficiency could lead to breast cancer progression However, whether RAD51 was acetylated by HDAC2 or SIRT2 was not discussed in detail." (PMID 33194676, 2020).
glioma (41 papers, 2006 to 2025). A benign or malignant brain and spinal cord tumor that arises from glial cells (astrocytes, oligodendrocytes, ependymal cells). "In vivo studies demonstrated that SIRT2 inhibitors slowed down the growth of ATRX-deficient glioma xenografts and also induced senescence in these tumors, suggesting a potential therapeutic strategy for treating this aggressive cancer type." (PMID 40710366, 2025). "Ectopic expression of SIRT2 in glioma cell lines disrupted the microtubule network causing a remarkable reduction in colony formation." (PMID 33014852, 2020). "Of these, SIRT2 and 7 have been associated with particular cancers with widely varying natural histories, SIRT2 with gliomas and SIRT7 with thyroid cancer." (PMID 17003781, 2006). "Similarly, SIRT2 inhibitors have shown promise in targeting ATRX (alpha-thalassemia mental retardation X-linked)-deficient gliomas, highlighting its role in driving oncogenic phenotypes in specific tumor subtypes." (PMID 40710366, 2025). "In glioma, the SIRT2 deacetylates G6PD, enhancing NADPH and pentose phosphate production, which supports the metabolic needs of rapidly proliferating tumor cells." (PMID 41428704, 2025). "SIRT2 activity is essential for the survival of glioma cells, and its reduction leads to both necrosis and caspase-3-dependent apoptosis of C6 glioma cells." (PMID 40710366, 2025). "This regulatory function of the SIRT2 is evident across multiple cancer types, including glioma, liver, lung, gastric, and colon cancers." (PMID 41428704, 2025). "Experiments with SIRT2 siRNA also demonstrate that decreased SIRT2 leads to both necrosis and apoptotic changes in C6 glioma cells." (PMID 40710366, 2025). "The transfer of SIRT2 to the nucleus is also observed inglioblastoma cells and other types of tumors, and patientswith higher SIRT2 in the nuclei of tumor cells have a worseprognosisfor glioma." (PMID 38680178, 2024). "Imaoka N., Hiratsuka M., Osaki M., Kamitani H., Kambe A., FukuokaJ., Kurimoto M., Nagai S., Okada F., Watanabe T., Ohama E.,Kato S., Oshimura M. Prognostic significance of sirtuin 2 proteinnuclear localization in glioma: an immunohistochemical study.Oncol.Rep." (PMID 38680178, 2024). "Schnekenburger and colleagues showed that their newly synthesized Compound 18 (identified via in silico screening, see Section 3.8) inhibits SIRT-1 and SIRT-2 with an anti-proliferative effect in glioma cells, both in in vitro and in vivo settings." (PMID 36080416, 2022). "In human glioma tumors and cell lines, SIRT2 deacetylates p65 at lysine 310 and inhibits miR-21 transcription through blocking p65 binding to the miR-21 promoter, suppressing the growth of glioma cells." (PMID 34769241, 2021). "By contrast, some studies also reported that SIRT2 overexpression enhanced tumor progression including cervical cancer, glioma, and NSCLC." (PMID 34697541, 2021). "SIRT2 inhibits colony formation in glioma cell lines and arrests chromosomal instability by getting down-regulated." (PMID 33597872, 2020). "SIRT2 and SIRT4, on the other hand, are considered tumor suppressor, downregulated in glioma and hepatocellular carcinoma (SIRT2), and bladder, gastric and lung cancer (SIRT4), among others." (PMID 32344886, 2020). "SIRT2 was reported to decrease in human gliomas, and colony formation ability was inhibited by the overexpression of SIRT2 in glioma cell lines in vitro." (PMID 31932479, 2020). "Northern blot analysis also revealed that RNA expression of SIRT2 was dramatically diminished in 12 out of 17 gliomas." (PMID 33014852, 2020). "In vitro colony formation ability was even shown to be reduced when SIRT2 was ectopically expressed in glioma cell lines." (PMID 31932479, 2020). "SIRT2 plays an important role in tumorigenesis and tumor progression and is frequently downregulated in various cancers, including human breast, liver, glioma, renal, prostate, lung, uterine, and basal cell carcinomas (20, –, 26)." (PMID 31932479, 2020).
glioma (continued). "Protein and mRNA levels of SIRT2 in five human glioma cell lines (T98G, U87MG, U251, A172, and CCF-STTG1) were also lower than two normal human astrocyte cell lines (NHA and HA)." (PMID 33014852, 2020). "Therefore, SIRT2 nuclear translocation may be associated with its oncogenic effects in glioma." (PMID 33014852, 2020). "They conclude in their study that SIRT2 suppresses glioma cell growth through targeting NF-kB-mIR-21 axis." (PMID 31119097, 2019). "Conversely, decreased SIRT2 activity can reduce glioma cell survival by induced both necrosis and apoptosis and limit melanoma cell growth and clonogenicity." (PMID 31727006, 2019). "Fluorescence microscopy of sections of rat brains revealed heterogeneously distributed patchy appearing circular-shaped regions of SIRT2 expression in 9L gliomas, as well as in the peripheral infiltrating zones." (PMID 29423902, 2018). "Studies also have showed that SIRT2 is involved in the tumorigenesis of many types of cancer, including non-small-cell lung cancer, glioma, melanoma and CRC." (PMID 28514749, 2017). "SIRT2 acts as a tumor suppressor gene in human gliomas through the regulation of microtubule network." (PMID 28514749, 2017). "The nanobubbles released sirtuin 2 (SIRT2) siRNA from the cationic micelles, resulting in a drastic reduction in tumor volume and an improvement in survival in the US nanobubble-treated C6 glioma xenograft tumor model." (PMID 28587119, 2017). "Human SIRT2 is most predominantly expressed in the brain and SIRT2 mRNA expression is severely reduced in approximately 70% of human gliomas." (PMID 25486244, 2014). "The SIRT family members (SIRT 1–7) are closely linked to carcinogenesis; carcinogenic roles of SIRT2 and SIRT7 have been documented in glioma and thyroid cancer, respectively." (PMID 25105144, 2014). "SIRT2 is downregulated in gliomas and gastric carcinomas, as well as in melanomas, in which a mutation in its catalytic domain has been shown to eliminate its enzymatic activity." (PMID 25486244, 2014). "SIRT2 has been reported to function as a tumor suppressor that is down-regulated in some human gliomas; however, its function has also been reported as essential for survival of C6 glioma cells." (PMID 24259290, 2013). "SIRT2 inhibition has been shown to induce apoptosis of such cell type as C6 glioma cells and HeLa cells." (PMID 24386592, 2013). "Sirtuin 2 may act as a tumor suppressor gene in human gliomas and be critical in human glioma via the NF-κB–miR-21 pathway." (PMID 40710366, 2025). "Researchers identified sirtuin 2 as a key player in the oncogenic features of these gliomas." (PMID 40710366, 2025). "The study concluded that SIRT2 expression and its localization could be indicative of glioma malignancy and may help predict patient survival, highlighting the potential of SIRT2 as a target for therapeutic strategies in treating glioblastoma." (PMID 40710366, 2025). "The study found a positive correlation between SIRT2-LI and the malignancy of gliomas." (PMID 40710366, 2025). "Some studies observed downregulation of SIRT2 in glioma and gastric cancer, suggesting that SIRT2 might play a suppressive effect in cancer development." (PMID 40421455, 2025). "SIRT2 overexpression inhibits miR-21 expression and is insufficient to reduce cell proliferation and colony formation or induce apoptosis when miR-21 is knocked down in glioma cells." (PMID 40710366, 2025). "HSP27 promotes glioma cell proliferation through SIRT2-mediated G6PD activation." (PMID 36639654, 2023). "It has been reported that SIRT2 mRNA expression is reduced in approximately 70% of human gliomas." (PMID 34359896, 2021). "Down regulation of Sirt2 levels in numerous cancer types such as gastric carcinoma, non-small lung cancer types and glioma imply that Sirt2 might be a tumor suppressor." (PMID 32698385, 2020). "HSPB1 also enhances proliferation via SIRT2-mediated G6PD activation in glioma cells." (PMID 32733879, 2020).
glioma (continued). "Fluorescence microscopy of tissue sections of intracerebral 9L gliomas growing in the rat brains stained with anti-SIRT2 fluorescent antibodies revealed heterogeneously distributed patchy-appearing circular regions of SIRT2 expression in core regions in peripheral infiltrating zones of 9L gliomas." (PMID 29423902, 2018). "To validate the results of PET/CT/MR imaging with 12[18F]DDAHA and to assess the cell specificity and heterogeneity of SIRT2 expression-activity in 9L gliomas and in different brain structures, we used immunofluorescent microscopy (IFM) in 9L glioma-bearing rat brain tissue sections." (PMID 29423902, 2018). "We identified SIRT2 as a downregulated protein in gliomas, and observed that exogenously expressed SIRT2 functions in the prophase to block the entry to chromosome condensation and subsequent hyperploid cell formation in glioma cell lines in response to mitotic stress." (PMID 27213315, 2016). "Besides, it is probable that combined treatment of glioma with SIRT2 or G6PD inhibitor would enhance anti-cancer effect of alkylating agent." (PMID 27711253, 2016). "Interestingly, AGK2 induces caspase-3-dependent apoptosis and necrosis of C6 glioma cells, while SIRT2 is downregulated in gliomas." (PMID 25486244, 2014). "Inhibitors targeting SIRT2 induce epigenome reprogramming in ATRX-deficient glioma models by modifying H3K27ac and H4K16ac marks on chromatin and causing genome-wide changes via enhancer-associated modifications, promoting senescence in the ATRX-deficient glioma model system." (PMID 39479502, 2024). "In addition, SIRT2 is located at 19q13.2, a region known to be frequently deleted in human glioma, thereby indicating that SIRT2 may be a tumor suppressor in gliomas." (PMID 33014852, 2020). "Notably, inhibition of SIRT2 activity decreased C6 glioma cells viability." (PMID 24259290, 2013). "Metformin regulates GBM cell lines through the circadian gene PER2 and the SIRT2/G6PD signaling pathway in a PER2-dependent manner, as well as through synergies with the radiotherapy sensitivity of glioma cells." (PMID 40166471, 2025). "SIRT2, which was identified through multiomics synthesis as a potential driver gene in ATRX-null gliomas, is overexpressed." (PMID 39479502, 2024). "HSPB1 activatedG6PD, the first and rate-limiting enzyme of pentose phosphate pathway, through enhancing SIRT2-mediated deacetylation of G6PD, hence protected glioma cells from oxidative stress and DNA damage." (PMID 27711253, 2016). "HSPB1 activates G6PD by promoting SIRT2-mediated G6PD deacetylation, thereby contributing to glioma cell survival and proliferation." (PMID 27711253, 2016). "SIRT2 expression was heterogeneous in ODII and ODIII gliomas,a subset of patients exhibiting a moderate increased expression, while most ofthem had decreased expression levels." (PMID 25791281, 2015). "Thus, inhibition of SIRT2 may become a new strategy for treating gliomas." (PMID 25486244, 2014). "We have found that strong inhibition of SIRT2 by 100 nM SIRT2 siRNA or 10 μM AGK2, a widely used SIRT2 inhibitor, can reduce the basal survival of PC12 cells and C6 glioma cells, thus suggesting toxic effects of strong inhibition of SIRT2." (PMID 24386592, 2013). "In glioma cells, however, it has been reported that several human glioma samples had reduced SIRT2 mRNA compared to normal brain tissue and that overexpression of SIRT2 decreased HTB14 glioma cells colony formation." (PMID 24259290, 2013). "HSPB1 enhanced SIRT2-mediated G6PD activation and promoted glioma cell proliferation." (PMID 36566214, 2022). "We found that, for both genes, copy number deletions were associated with lower mRNA expression, and in gliomas without HDAC1 or SIRT2 copy number variations, patients with lower HDAC1 expression or higher SIRT2 expression showed better clinical prognosis." (PMID 33718432, 2021).
glioma (continued). "Interestingly, the expression of SIRT2 is absent in human glioma cells, and re-expression of SIRT2 can reduce the ability of colony-stimulating factor formation of cells." (PMID 36359005, 2022). "The roles of SIRT1, SIRT2, SIRT3, and SIRT7 in glioma are not comprehensively understood." (PMID 36568393, 2022). "Therefore, to exclude the potential influences of 1p/19q codeletion, we compared the mRNA expression levels of HDAC1 and SIRT2 according to CNV status, as well as the OS rates between low and high levels of HDAC1 and SIRT2 mRNA expression in gliomas without HDAC1 or SIRT2 CNVs." (PMID 33718432, 2021).
Obesity (38 papers, 2016 to 2026). Accumulation of substantial excess body fat. "SIRT2 knockout mouse displayed increased susceptibility to obesity, liver injury, and metabolic dysfunction when placed on high fat/high sucrose/high cholesterol diet." (PMID 40136715, 2025). "Second, Sirt2 deficiency resulted in significant primary obesity and insulin resistance accompanied by hepatic metabolic dysfunction." (PMID 39004743, 2024). "Here, we constructed Sirt2 knockout and adeno-associated virus overexpression mice and found that deletion of hepatic Sirt2 accelerated primary obesity and insulin resistance in mice with concomitant hepatic metabolic dysfunction." (PMID 39004743, 2024). "Here, we found that Sirt2 deficiency led to impaired glucose tolerance and insulin resistance and induced primary obesity." (PMID 39004743, 2024). "Our study found that SIRT2 deficiency exacerbated hepatic steatosis, inflammation, and fibrosis, while also impairing insulin sensitivity and aggravating obesity." (PMID 37240315, 2023). "Since we previously observed that SIRT2 deficiency significantly aggravated HFCS-induced obesity and hepatic lipid storage, we next examined in more detail of the liver sections of SIRT2 KO and SIRT2 WT mice." (PMID 37240315, 2023). "We showed that the SIRT2 KO mice were more susceptible to HFCS-induced obesity and hepatic steatosis." (PMID 37240315, 2023). "We found that SIRT2 deficiency in mice exacerbates HFD-induced obesity, glucose intolerance, and insulin resistance." (PMID 35743232, 2022). "In combination, these findings suggest that the loss of SIRT2 aggravates dietary-induced obesity and results in unhealthy expansion of visceral adipose tissue." (PMID 35743232, 2022). "We have implicated SIRT2 in prolonged immunosuppression in vivo in obesity with sepsis mice, via NFκB p65 deacetylation and deactivation." (PMID 36865524, 2022). "Here, Watanabe and colleagues show that impaired hepatic glucose uptake during obesity is caused by a reduction in Sirt2 activity, which promotes glucokinase regulatory protein acetylation and its dissociation from glucokinase." (PMID 29296001, 2018). "Hif1a is associated with dietary obesity by restricting fatty acid oxidation through repression of SIRT2." (PMID 28445509, 2017). "Sirtuin 2 (SIRT2) deficiency promoted lipid deposition and inflammation in cells accompanied with HFCS (high-fat/high-cholesterol/high-sucrose)-induced obesity, hepatic steatosis, and an aggravated metabolic profile, indicating SIRT2 deficiency advances NAFLD–NASH progression." (PMID 38283696, 2024). "Here, we report that SIRT2 knockout (KO) mice are susceptible to HFCS (high-fat/high-cholesterol/high-sucrose)-induced obesity and hepatic steatosis accompanied with an aggravated metabolic profile, which indicates SIRT2 deficiency promotes NAFLD-NASH (nonalcoholic steatohepatitis) progression." (PMID 37240315, 2023). "An obesity- and aging-associated decline in NAD+ content and SIRT2 activity in hypothalamic microglia might exaggerate microglial activation and hypothalamic inflammation and accelerate systemic aging and obesity." (PMID 32143417, 2020). "Our results found that Sirt2 deficiency led to impaired glucose tolerance and insulin resistance and that KO mice had a higher diet and body weight but reduced caloric expenditure and developed significant primary obesity with concomitant hepatic metabolic dysfunction." (PMID 39004743, 2024). "SIRT2 modulates sepsis inflammation and OA development in the context of obesity by inhibiting oxidative stress, while increased oxidative stress and cysteine (C221 and C224) thiol oxidation exacerbate hyper-inflammation." (PMID 39372420, 2024). "In this study, we determined the protective role of Sirt2 in liver injury, obesity-related insulin resistance, and glucose metabolism." (PMID 39004743, 2024).